C13orf42 (chromosome 13 open reading frame 42)
Synonyms: LINC00371; LINC00372
Gene: Protein-coding gene on chromosome 13 (51,082,119 to 51,200,252, reverse strand). Ensembl gene ENSG00000226792.
Homologues: Orthologues: chimpanzee C13orf42 (99% identical), macaque C17H13orf42 (98% identical), guinea pig C13orf42 (85% identical), rabbit C13orf42 (82% identical), pig C13orf42 (78% identical), rat C15h13orf42 (78% identical), mouse Gm4131 (77% identical).
Diseases named in the same sentence as C13orf42 in open-access papers:
C13orf42 is named in the same sentence as 2 diseases in open-access papers, as found by Europe PMC text mining. Sharing a sentence is not in itself a finding about the gene and the disease. The quoted sentences say what the papers report.
Bardet-Biedl syndrome (1 paper, 2025). A ciliopathy with multisystem involvement. "To date, C13orf42 has only been demonstrated to be related to Bardet-Biedl syndrome." (PMID 40608007, 2025).
breast carcinoma (1 paper, 2025). "Chromosome 13 open reading frame 42 (C13orf42), lactalbumin alpha (LALBA), G protein-coupled receptor class C group 5 member A (GPRC5A), and GC vitamin D binding protein (GC) have been identified as the most highly expressed genes in breast cancer." (PMID 40608007, 2025).